KEAP1 (kelch like ECH associated protein 1)
Diseases named in the same sentence as KEAP1 in open-access papers (continued):
Sharing a sentence is not in itself a finding about the gene and the disease.
lung carcinoma (continued). "According to the cBioPortal cancer genomic database, in a curated set of non-redundant studies, KEAP1 gene mutations are found in around 3% of samples; the highest percentage of KEAP1 mutations is found in lung cancer (13–16%), lung adenocarcinoma (15%), and non-small-cell lung cancer (NSCL, 13%)." (PMID 39941813, 2025). "NRF2 and its negative regulator KEAP1 are commonly mutated in human lung cancers, leading to NRF2 accumulation and constitutive expression of NRF2 target genes, many of which are at the interface between antioxidant function and anabolic processes that support cellular proliferation." (PMID 40334547, 2025). "Pharmacological inhibition of this axis has been found to induce radiotherapy sensitivity in kelch-like ECH-associated protein 1 (KEAP1)-deficient lung cancer (a frequent subtype of lung cancer that resists chemotherapy and radiotherapy) through inducing ferroptosis." (PMID 40227202, 2025). "Furthermore, a human lung cancer cell line with KEAP1 mutation, H460, was used to explore the effect of KEAP1 in itaconate-induced radioresistance." (PMID 40482348, 2025). "The first cell lines harboring Keap1 mutations were obtained from human lung cancer." (PMID 40769273, 2025). "Oncogenic KEAP1 mutations activate TRAF2-NFκB signaling to prevent apoptosis in lung cancer cells." (PMID 40612112, 2025). "These drugs may have adjuvant therapeutic effects in patients with KEAP1-mutated lung cancer and need further exploration." (PMID 38962454, 2024). "Importantly, suppression of CoQ-FSP1 was found to increase the sensitivity of KEAP1-deficient lung cancer cells to radiation through inducing ferroptosis." (PMID 38705513, 2024). "Recently, we could show that the co-mutations of KRAS + KEAP1, STK11 + KEAP1 and KRAS + STK11 + KEAP1 lead to a significantly shorter median overall survival (mOS) in patients with lung cancer across treatments by analyzing multiple dataset." (PMID 39156705, 2024). "Kelch-like ECH-associated protein 1 (KEAP1) in lung cancer typically mutates or is inactivated." (PMID 38590315, 2024). "Keap1 is an inhibitor of Nrf2 and is mutated or inactivated in lung cancers." (PMID 38705513, 2024). "Current evidence suggests that mutations in the NRF2/KEAP1 gene may lead to poor prognosis in patients with lung cancer, such as resistance to radiotherapy and chemotherapy, but more specific evidence is needed to validate this 25,26." (PMID 38169561, 2024). "This enhanced ability to produce NADPH is vital for offsetting the heightened consumption of NADPH by FSP1 during the production of CoQH2, which could also contribute to the resistance to ferroptosis observed in KEAP1 deficient lung cancer cells." (PMID 38206305, 2024). "The results suggest that KEAP1 mutations in cluster 1 might have an NRF2-independent role in regulating apoptosis in lung cancer cells." (PMID 38184997, 2024). "STK11 and KEAP1 have been associated with a poorer prognosis in KRAS mutant lung cancer." (PMID 38067288, 2023). "Similarly, the small molecule inhibitor ML385, which interferes with DNA binding of the transcriptional complex containing NRF2 for the target gene, sensitized KEAP1-deficient lung cancer cells to carboplatin." (PMID 35053572, 2022). "FSP1 inhibition (using a FSP1 inhibitor iFSP1 or deleting FSP1 expression) largely promoted radiosensitization and IR-induced lipid peroxidation in KEAP1 deficient of mutant lung cancer cells, making FSP1 an ideal target for targeted treatment during radiotherapy." (PMID 36264074, 2022). "In this study, we showed that FSP1 is overexpressed in KEAP1 mutant lung cancers and that FSP1 is required for xenograft tumor growth in KEAP1 deficient lung cancers, further nominating FSP1 as a promising therapeutic target for treating KEAP1 deficient lung cancers." (PMID 35459868, 2022).
lung carcinoma (continued). "Furthermore, changes of genetic background which leading SLC7A11 up-regulation such as KEAP1 mutation, can impose metabolic vulnerability of lung cancer cells to GLUTs inhibitors." (PMID 35178349, 2022). "Similarly, NRF2 transcriptionally activates ferroptosis suppressor protein 1 (FSP1), which mediates ferroptosis- and radiation-resistance in KEAP1-mutated lung cancer cells." (PMID 36282248, 2022). "We further studied whether inactivating FSP1 sensitizes KEAP1 deficient or mutant lung cancer cells to RT." (PMID 35459868, 2022). "Some previous studies demonstrated that Nrf2 transient knockdown or selective inhibition through the Keap1 overexpression strongly increased the susceptibility of lung cancer cells to different chemotherapeutics, including cisplatin, doxorubicin, and etoposide." (PMID 35646695, 2022). "However, regardless of TMB and PD-L1 status, the presence of STK11/LKB1 and KEAP1 mutations is a poor prognosis factor in lung cancer." (PMID 35407463, 2022). "Importantly, KEAP1 deficiency-induced ferroptosis resistance to RSL3 or ML162 in these lung cancer cells was largely abolished under CoQ synthesis blockade conditions (by 4-chlorobenzoic acid [4-CBA] treatment)." (PMID 35459868, 2022). "It is hypothesised that Nrf2/Keap1 mutations are prominent in lung cancer because hyper-activation of Nrf2 signalling can be beneficial to lung cells constantly exposed to oxygen and chemicals from the air." (PMID 34202320, 2021). "The majority of mutations in Nrf2 and Keap1 identified have been found in a lung cancer background." (PMID 34202320, 2021). "Additionally, inhibition of the PI3K/AKT pathway markedly reduces endogenous NRF2 protein and enzymes in KEAP1-mutant lung cancer cells and KEAP1-deficient mouse embryonic fibroblasts (MEFs)." (PMID 33922165, 2021). "Likewise, deficiency of the tumor suppressor KEAP1 (which is frequently mutated in lung cancer) inhibited IR-induced ferroptosis at least partly through stabilizing NRF2 and upregulating SLC7A11, leading to radioresistance." (PMID 33891303, 2021). "Furthermore, our results are relevant to the debate on the promises and perils of antioxidant supplementation, especially for lung cancer patients and for the 30% of them who harbor KEAP1/NRF2 mutations." (PMID 34226519, 2021). "Furthermore, Keap1 genetic mutations have been found in 25–30% of lung cancer patients with 41% of these cases having a loss of function mutation." (PMID 34202320, 2021). "High-frequency mutations in KEAP1 have been identified in Chinese patients with lung squamous cell carcinoma, while the somatic nonsynonymous mutation of KEAP1 in patients with lung cancer is likely to promote tumorigenesis via activation of the KEAP1/NRF2 antioxidant stress response pathway." (PMID 34248926, 2021). "Furthermore, CP alone or in combination with rapamycin strongly inhibited the in vitro and in vivo growth of tumors harboring mutations in Keap1 or both Keap1 and Lkb1 frequently observed in lung cancer." (PMID 34384473, 2021). "Moreover, many Keap1 mutations or loss of heterozygosity in the Keap1 locus has been identified in lung cancer." (PMID 32206121, 2020). "Combining both epigenomic and transcriptomic changes along with KEAP1 mutations may provide a better understanding of the molecular mechanisms associated with the progression of lung cancer and may help to provide better therapeutic approaches." (PMID 32327612, 2020). "Therefore, targeting glutaminolysis using glutaminase inhibitors presents a promising therapeutic approach for aggressive subtypes of lung cancer with mutations in KEAP1/NRF2." (PMID 32112372, 2020). "CB-839, a glutaminase inhibitor, inhibits the growth of KARS and Keap1 co-mutated lung cancer." (PMID 33324555, 2020).
lung carcinoma (continued). "ROS levels were significantly decreased in lung cancer cells with KEAP1 mutation." (PMID 32576270, 2020). "KEAP1 mutation is correlated with poor prognosis of lung cancer." (PMID 32206449, 2020). "Thus, it is tempting to presume that inhibitors of the KEAP1/NRF2 pathway will likely treat Lung cancer patients carrying KEAP1/NRF2 mutations." (PMID 32576270, 2020). "Furthermore, KEAP1 mutations showed significant positive correlation with SOX9 expression in the TCGA lung cancer cohort." (PMID 33173725, 2020). "Actually, increasing attention to the KEAP1 gene in lung cancer is mainly due to point mutations that show great translational impact in terms of increased risk of cancer progression, shorter overall survival and response of NSCLC patients’ to chemo and biological treatments." (PMID 32971994, 2020). "KRAS is the most common driver mutation in lung cancer, and is highly co-occurrent with KEAP1 and STK11 mutations, NOTCH1 has a putative role in skin cancer, loss of PTEN is the most common genomic alteration in glioblastoma, and DNMT3A has been associated with leukemia and myelodysplasia." (PMID 32374727, 2020). "We further collected all available 7 lung cancer cell lines and found three of them carried the KEAP1 mutation (A549, NCI-H460, NCI-H838), thus, in the present study, all the seven lung cancer cell lines were used to study the influence of KEAP1 mutation on the function of KEAP1/NRF2 pathway." (PMID 32576270, 2020). "In lung cancer tissues, the presence of epigenetic abnormalities in the KEAP1 gene plus its point mutations/LOH matched with the prevalence of NRF2 nuclear accumulation in NSCLC tissues and was associated with an increased risk of lung cancer progression in surgically resected patients." (PMID 31159323, 2019). "Of note, somatic mutations in Keap1 (e.g. G333C, G350S, L413R, D236H) and the methylation of the Keap1 promoter are frequently observed in lung cancer whereas Nrf2 mutations (e.g. W24C, E82D, D77V) happen more often in esophageal cancer, which have been reviewed recently." (PMID 31511020, 2019). "As a consequence, we supposed that the hypermethylation of the P1 KEAP1 promoter might lead to the loss of SP-1 and AP-2 binding via inhibiting its expression at the first two, 4th and 5th CpG sites in the analyzed lung cancer cells, respectively." (PMID 31159323, 2019). "In support of our hypothesis, several lung cancers harboring KEAP1 mutations have increased expression of WDR23, ranging from 2.06 to 4.8-fold." (PMID 28453520, 2017). "Somatic mutations in KEAP1 were reported to occur in 60% of lung cancers." (PMID 27703446, 2016). "Additionally, Nrf2 overexpression was shown to activate FSP1, further reducing lipid free radical production by lowering CoQ10 and inhibiting ferroptosis from occurring in lung cancer, mediating resistance to ferroptosis and radiation in Keap1-deficient lung cancer cells." (PMID 39557840, 2024). "Similarly, AKT inhibitor was used in lung cancer with KEAP1 mutation through interaction of cellular antioxidant pathway and could assist to kill tumor cell." (PMID 38962454, 2024). "Additionally, other research has found that somatic mutations and gene variations in KEAP1 frequently occur in lung cancers and cancer-derived cell lines, suggesting that mutation KEAP1 might disrupt its ability to bind NRF2." (PMID 39500864, 2024). "Therefore, combining FSP1 inhibitors may represent an effective therapeutic strategy for ferroptosis in Keap1-deficient lung cancer and cancers with radioresistance." (PMID 39557840, 2024).
lung carcinoma (continued). "Furthermore, KEAP1/NRF2 mutations in patients with NSCLC seems to correlate with an increase in local recurrence after RT suggesting that KEAP1/NRF2 status is predictive for local recurrence after RT in patients with lung cancer." (PMID 36046142, 2021). "Notably, NRF2 inhibitor ML385 may inhibit the proliferation of tumor cells with KEAP1 mutation by enhancing the oxidative stress level of lung cancer cells." (PMID 32576270, 2020). "Interestingly, compared with the lung cancer cell lines A549 and H460, which carry KEAP1 mutation, after stable transfection with WT KEAP1, the mRNA levels of NRF2 and its target genes are significantly increased in A549 and H460 lung cancer cell lines transfected with KEAP1 mutants." (PMID 32576270, 2020). "Interestingly, heterozygous KEAP1 mutations frequently occur in lung cancers." (PMID 23272301, 2012). "To investigate how these genetic alterations drive tumor formation, we conducted CRISPR screens on metabolically stressed murine lung cancer models and identified specific cancer dependencies, including ubiquitin ligase subunit KEAP1." (PMID 41862643, 2026). "KEAP1 deficit in lung cancer cells, therefore, resulted in enhanced antioxidant defense and resistance to ferroptosis inside these cells." (PMID 40227202, 2025). "To address this question, we established a syngeneic mouse model using the transplantation of 3LL lung cancer-derived cells with either NRF2 hyperactivation via Keap1 gene deletion or concomitant Keap1-Nrf2 gene deletion." (PMID 41035689, 2025). "The reason for this stems from the differences in both response to FTIs and differences in ferroptosis defense systems where STK11/KEAP1-mutant lung cancer harbors very effective anti-ferroptosis systems through SLC7A11/GPX4, AIFM2, and AKR1C." (PMID 39995872, 2025). "KEAP1-mutant lung cancers represent a highly treatment-resistant patient subset, underscoring the need for further study to better understand and target these tumors." (PMID 41462606, 2025). "We generated murine 3LL lung cancer cell lines with NRF2 activation by deleting the Keap1 gene using the CRISPR-Cas9 genome editing method." (PMID 41035689, 2025). "To assess the impact of KEAP1/STK11 mutations on immune profiles, we analyzed RNA-seq data from the TCGA lung cancer cohort and the GSE72094 cohort." (PMID 41378285, 2025). "This large cohort study contains mutational data for KRAS, KEAP1 and NFE2L2 from 853 lung cancer patients." (PMID 40890297, 2025). "Our current study builds on these prior findings and directly evaluates the efficacy of triterpenoid derivatives in treating KEAP1-mutant murine lung cancer." (PMID 41462606, 2025). "To access the impact of KEAP1/STK11 mutations on immune landscape of lung cancer, we utilized two bulk RNA-seq datasets: TCGA-lung cancer and GSE72094, for our analysis." (PMID 41378285, 2025). "Clinical translation exploration: Validating the efficacy of combinations such as DRP-104 with immune checkpoint blockers in specific subgroups, for instance, KEAP1-mutant lung cancer." (PMID 41041303, 2025). "As consequence, in lung cancer cells this binding is inhibited due to hypermethylation, suggesting the epigenetic interference in the modulation of KEAP1 expression in cancer cells." (PMID 40563292, 2025). "Deactivating FSP1 with a synthetic inhibitor iFSP1 markedly enhanced the post-IR lipid peroxidation in several KEAP1-mutant lung cancer cell lines and potentiated efficient lung cancer elimination." (PMID 41041050, 2025). "Research has found that KEAP1 inactivation results in glucose dependence, rendering lung cancer cells sensitive to glucose inhibitors." (PMID 40083325, 2025).
lung carcinoma (continued). "KEAP1 inactivation is a known contributor to lung cancer, and KEAP1 zygosity was recently found to predict drug sensitivity and therapeutic response." (PMID 40600748, 2025). "We generated 3LL lung cancer cell lines with NRF2 hyperactivation by means of the Keap1 gene deletion and those with KEAP1-NRF2 concomitant deletion using the genome editing technology." (PMID 41035689, 2025). "Artesunate activates the protective Keap1/Nrf2 pathway in lung cancer cells, improving cellular antioxidant defenses." (PMID 41347152, 2025). "We report that KEAP1-mutant LL2 murine lung cancer cells directly regulate macrophages to promote their pro-tumor differentiation and the abundance of this macrophage subset within the tumor microenvironment." (PMID 41462606, 2025). "To characterize the immunomodulatory effects of triterpenoids in KEAP1-mutant lung cancer, we studied tumor-educated bone marrow-derived macrophages (TE-BMDMs) and lung cancer models treated with the triterpenoids CDDO-Me or omaveloxolone." (PMID 41462606, 2025). "It is noteworthy that SMARCA4 loss in human lung cancer is associated with enhanced NRF2 target expression; this effect can be recapitulated in vitro where SMARCA4 knockdown inactivates KEAP1, activates NRF2 and enhances haem oxygenase 1 expression." (PMID 40069402, 2025). "Considering all this evidence supporting the role of NRF2/KEAP1 signaling pathway in lung cancer development, this opens NRF2 as a new therapeutic target to develop antineoplastic treatments for lung malignancies." (PMID 41008623, 2025). "This manuscript investigates how synthetic triterpenoid derivatives affect KEAP1-mutant lung cancer growth, with a specific focus on the role of the immune system." (PMID 41462606, 2025). "In this study, we have evaluated immune cell infiltration in a syngeneic mouse model using the transplantation of 3LL lung cancer-derived cells with either NRF2 hyperactivation via Keap1 gene deletion or concomitant Keap1-Nrf2 gene deletion." (PMID 41035689, 2025). "The KEAP1-Nrf2 pathway’s primary downstream effector is FSP1/CoQ10, which is found in KEAP1-mutant lung cancer and identified as a critical therapeutic target." (PMID 38590315, 2024). "To assess, we generated CRISPR-edited mouse lung cancer cell lines by knocking out the KEAP1 or NFE2L2 genes and utilized a publicly available single-cell dataset through the Gene Expression Omnibus to investigate tumor/immune cell interactions." (PMID 38542481, 2024). "Overall, the results suggest that TRAF2-NFκB activation in KEAP1 R320Q and R470C overexpressing A549 cells protects lung cancer cells against apoptosis and that XIAP and BIRC family of proteins regulate the process." (PMID 38184997, 2024). "It has been discovered that inhibiting CoQ10 synthesis can overcome the radiation resistance of lung cancer cells or KEAP1-deficient or mutated tumors, inhibiting FSP1 makes KEAP1-deficient lung cancer cells radiosensitive by inducing ferroptosis." (PMID 38590315, 2024). "A similar trend was observed in lung cancer cell line A549, where an ROS inductor, hydrogen peroxide, decreased protein expression of KEAP1." (PMID 39408587, 2024). "Recent studies have identified concurrent mutations in STK11 and KEAP1 that appear to protect against ferroptosis and promote SCD1 dependence in lung cancer." (PMID 38383297, 2024). "In KEAP1 mutant cell lines, it has been widely reported, firstly in lung cancer, that KEAP1 hardly regulates NRF2 activation, and NRF2 protein levels are high." (PMID 38791966, 2024). "KEAP1 and STK11 mutations have been identified as associated with immunotherapy resistance in lung cancer." (PMID 39723373, 2024).